CHRNA5 (cholinergic receptor nicotinic alpha 5 subunit)
Diseases named in the same sentence as CHRNA5 in open-access papers (continued):
Sharing a sentence is not in itself a finding about the gene and the disease.
tumor (17 papers, 2013 to 2025). "CHRNA5 further promoted mesenchymal features, was linked to disseminated tumor patterns, and predicted poor prognosis." (PMID 41201200, 2025). "In agreement with a pro-tumour role, high overall CHRNA5 transcription was associated with worse prognosis in LUAD." (PMID 40336011, 2025). "Signaling pathways initiated by neurotransmitter receptors, such as α5-nicotinic acetylcholine receptor (CHRNA5), have been reported to be implicated in tumor progression." (PMID 35214008, 2022). "The results suggested that there was a close association between the CHRNA5 mRNA expression level and tumor stage, suggesting that CHRNA5 plays a role in tumor progression." (PMID 35214008, 2022). "The polymorphism CHRNA5 can be considered an indirect risk factor for neoplasms in these Brazilian samples when cigarette consumption increased." (PMID 31599127, 2019). "As a type of membrane protein, CHRNA5 is involved in the occurrence and development of tumours through various pathways." (PMID 38879667, 2024). "We found that the tumor volume in nude mice significantly decreased with knockdown of CHRNA5 (p < 0.0001), and nicotine treatment increased the tumor volume (p < 0.001)." (PMID 39472448, 2024). "Subsequent western blot experiments on tumor tissue proteins revealed that activation of MEK (p-MEK/MEK) significantly decreased under CHRNA5 knockdown (p < 0.001), whereas nicotine reversed the reduction of p-MEK/MEK in the SH group." (PMID 39472448, 2024). "On the other hand, CHRNA5 can affect the sensitivity of tumour cells to radiotherapy and chemotherapy." (PMID 38879667, 2024). "Conversely, the expression levels of IL6 and CHRNA5 were lower in tumor-free patients after initial treatment compared to those who still had remaining tumors." (PMID 37509183, 2023). "The results revealed that CHRNA5 silencing significantly inhibited tumor growth, and CHRNA5 overexpression markedly promoted tumor growth in vivo, further suggesting that CHRNA5 plays a critical role in promoting the proliferation ability of HCC cells." (PMID 35214008, 2022). "The results reveal that CHRNA5 expression level is upregulated in HCC tissues and is closely associated with tumor T stage, AJCC phase, and patient prognosis." (PMID 35214008, 2022). "Two variants in these regions, rs578776 (CHRNA3, OMIM:118503) and rs16969968 (CHRNA5, OMIM:118505), have been associated with both smoking behavior, including smoking quantity, and certain types of neoplasms, for example, HNC." (PMID 31599127, 2019). "A direct effect of CHRNA5 expression on tumour cell-intrinsic growth, migration and invasion has been supported by several in vitro studies, although the outcome is likely dependent on the expression pattern of other nAChR subunits expressed in each experimental system." (PMID 40336011, 2025). "Moreover, mice in the sh-CHRNA5 group had fewer pan-cytokeratin-positive tumour cells in the inguinal lymph nodes than mice in the sh-NC and sh-CHRNA5 + nicotine groups." (PMID 38879667, 2024). "Additionally, higher expression levels of PDAP1 and CHRNA5 were found in patients who experienced new tumor events after initial treatment." (PMID 37509183, 2023). "The role of CHRNA5 in tumor proliferation was previously reported." (PMID 35214008, 2022). "Furthermore, the inhibitory effects of silencing CHRNA5 on the tumor spheroid formation ability of PLC cell lines and the expression of stemness-associated genes were also attenuated after overexpressing YAP." (PMID 35214008, 2022). "Therefore, the effects of CHRNA5 RNAi on cell-cell junctions and differentiation are promising and can be further studied for their roles in tumor progression." (PMID 30543688, 2018). "Interestingly, in addition to CHRNA7, only a few other nAChR subunit genes modified their expression due to the effect of tobacco (CHRFAM7A, CHRNA5, CHRNA9) or to the degree of tumor differentiation (CHRNA5), but these changes only happen in SQC-L tumors." (PMID 28978081, 2017).
tumor (continued). "On the other hand, changes related to α3 and α5 mRNA levels found in SQC-L and ADC-L tumors in our study concur with a previous paper describing transcriptional dysregulation for CHRNA3 and CHRNA5 in lung tumor biopsies paired with their corresponding non-tumor specimens from 21 patients with ADC-L." (PMID 28978081, 2017). "The protein expression level of CHRNA5 in the SH group was lower than that in the NC group, with a significantly lower immunohistochemical score (H-score) than that in the NC group (p < 0.05), further confirming the successful construction of the Cal27 cell nude mouse tumor model." (PMID 39472448, 2024). "The transcriptomes (scRNA‐seq) of 2215 tumor cells from 18 HNC patients were analyzed, in which CHRNA5‐dominant cells were the most (47%), followed by the cells lacking expression of CHRNA3, CHRNA5, and CHRNA7 (41%)." (PMID 41201200, 2025). "In HNC, CHRNA5 was found to mediate nicotine‐induced proliferation, migration, and invasion by regulating CES1 via the MEK/ERK pathway, contributing to tumor recurrence and metastasis." (PMID 41201200, 2025). "On the one hand, CHRNA5 can activate multiple signalling pathways, such as TGF-β1–Smad, JAK2/STAT3 and Notch1, thus promoting tumour cell proliferation, survival and metastasis." (PMID 38879667, 2024). "Compared with patients without a smoking history, those with a smoking history (including both former and active smokers) had significantly higher RABL6 expression in tumour tissues and more pronounced co-localisation of RABL6 with CHRNA5." (PMID 38879667, 2024). "In the TCGA-HNSC cohort, we observed the expression of 12 ion channel genes in tumor and normal tissues; ANO1, AQP9, BEST2, CHRNA5, and KCNJ15 were upregulated in HNSCC, while AQP1, AQP5, SCNN1G, and SCN4A were downregulated." (PMID 36389709, 2022). "This is consistent with our IHC findings, where tumor infiltrations had higher CHRNA5 levels than tumor islands, which was not the case for CHRNA3 and CHRNA7." (PMID 41201200, 2025). "CHRNA5 expression was higher in neoplastic tissues of current smokers than that of lifelong non-smokers (p < 0.01) and increased with increasing grade (p < 0.05), TNM stage (p < 0.05) and tumour size (p < 0.01)." (PMID 38879667, 2024). "Tumor western blot experiments and qRT-PCR validation confirmed that p-MEK/MEK, p-ERK/ERK, and CES1 levels decreased with the knockdown of CHRNA5, whereas nicotine reversed this trend in the SH group, indicating that CHRNA5 regulates CES1 expression through the MEK/ERK pathway." (PMID 39472448, 2024). "Further in vitro assays revealed that CHRNA5 could regulate YAP activity, and YAP silencing was sufficient to reverse the CHRNA5-mediated tumor-promoting effect." (PMID 35214008, 2022). "The results showed that silencing CHRNA5 inhibited the tumor spheroid formation ability of PLC cells, and CHRNA5 overexpression increased the tumor sphere formation ability of Huh7 cells, indicating that CHRNA5 has a regulatory role in maintaining the stemness properties of HCC cells." (PMID 35214008, 2022). "In this study we have also shown that CHRNA5 RNAi might result in reduced DNA damage response (DDR) based on TCGA and METABRIC tumor data, and GSEA and DAVID functional analyses as well as quantification of total and phosphorylated CHEK1 protein levels." (PMID 30543688, 2018). "To test the effects of CHRNA5 depletion we used a CHRNA5 RNAi model in MCF7 cells and performed microarray expression analysis showing coordinated transcriptomic changes in multiple pathways involved in tumor formation and progression." (PMID 30543688, 2018). "Quite strikingly, tumor size and tumor weight were significantly lower in cells treated with the CHRNA5 shRNAmirs vs. the non-silencing shRNAmir control (n = 9)." (PMID 24062692, 2013). "CHRNA5, CHRNA10, CHRNB4, CHRND, CHRNE, and CHRNG, however, were not expressed at levels significantly different from the non-tumor control samples." (PMID 31590360, 2019).
adenocarcinoma (3 papers, 2018 to 2021). A common cancer characterized by the presence of malignant glandular cells. "The enrichment was stronger and more extensive in the squamous cell type, which had three loci associated with SCZ, and only one with adenocarcinoma (the CHRNA3/CHRNA5/CHRNB4 cluster on chromosome 15q25.1)." (PMID 29330379, 2018).
cardiovascular disease (2 papers, 2015 to 2024). "Therefore, further studies with larger samples and a broader population range are necessary to determine the true association between CHRNA5-CHRNA3-CHRNB4 polymorphism and cardiovascular disease." (PMID 25874685, 2015).
head and neck tumor (1 paper, 2024). "Nicotine enhances the proliferation, migration, and invasion abilities of head and neck tumor cells by promoting the expression of CHRNA5." (PMID 39472448, 2024).
CHRNA5 also shares sentences with these, for which no sentence is quoted: neuroblastoma (3 papers); alcohol (2); head and neck squamous cell carcinoma (2); peripheral artery disease (2); amyloid (1); aortic aneurysm (1); asthma (1); bipolar disorder (1); brain disorder (1); Cluster headache (1); cognitive (1); emphysema (1); epilepsy (1); esophageal squamous cell carcinoma (1); immune system disease (1); infectious disease (1); ischemic stroke (1); microcephaly (1); neurodevelopmental disorder (1); Parkinson disease (1); proctitis (1); psychiatric disorder (1); respiratory system diseases (1); squamous cell carcinoma (1); stomach cancer (1); vascular intestinal disorders (1).